ALDH1A1 (aldehyde dehydrogenase 1 family member A1)
Diseases named in the same sentence as ALDH1A1 in open-access papers (continued):
Sharing a sentence is not in itself a finding about the gene and the disease.
glioma (37 papers, 2015 to 2025). A benign or malignant brain and spinal cord tumor that arises from glial cells (astrocytes, oligodendrocytes, ependymal cells). "In 2015, high ALDH1A1 expression was found to be associated with highly aggressive tumor cells and high-grade gliomas." (PMID 36091753, 2022). "Besides, ALDH1A1 and ALDH1A2 have been documented as glioma migration-associated genes, while ALDH1A1 also participated in GBM resistance to temozolomide." (PMID 35116021, 2021). "As reported, aldehyde dehydrogenase 1A1 (ALDH1A1) can serve as a marker for glioma stem cells; moreover, ALDH1A1+ cells were increased in the invasive frontier area compared with the non-invasive frontier area." (PMID 38041196, 2023). "Evidence supports that ALDH1A1’s expression is higher in high-grade gliomas than in low-grade gliomas, whereas ALDH1A3 is expressed in most GBM cases but not in normal tissues and low-grade gliomas." (PMID 37686694, 2023). "It has also been revealed that ALDH1A1 and peroxiredoxin 4 are direct targets of β-catenin and contribute to glioma invasiveness." (PMID 36046036, 2022). "USF1/SNHG16/miR-212–3p/ALDH1A1 and USF1/linc00667/miR-429/ALDH1A1 axis regulates the VM of glioma cells." (PMID 34803608, 2021). "In the LGG cohort from the TCGA dataset, ALDHs including ALDH2, ALDH6A1, ALDH5A1, ALDH9A1, ALDH1A1 were upregulated in WHO grade II gliomas while the increased expression of ALDH16A1, ALDH3B1, ALDH3A2, ALDH1A2, ALDH3A1 was found in WHO III grade gliomas." (PMID 35116021, 2021). "In our study, ALDH1A1 presented a significantly decreased expression in HGG than that in LGG gliomas." (PMID 26575197, 2015). "Though generally believed to be responsible for the ALDH activity of CSCs of many cancers, ALDH1A1 was a poor prognostic indicator in gliomas." (PMID 26575197, 2015). "In previous studies, ALDH1A3 and ALDH1A1 were supposed to be two important ALDH isoforms in gliomas." (PMID 26575197, 2015). "However, the same source indicates that lower mRNA levels of ALDH1A1 and ALDH1A3 in high-grade gliomas are associated with an increased proportion of patients surviving more than 3 years." (PMID 39001459, 2024). "ALDH1A1 promoted glioma progression, invasion, and proliferation, and led to poor prognosis." (PMID 36091753, 2022). "Thus, the E-cadherin/β-catenin/ALDH1A1 and E-cadherin/β-catenin/peroxiredoxin-4 pathways are likely direct promoters of anoikis resistance in glioma." (PMID 36046036, 2022). "Isoforms ALDH1A1 and ALDH1A3 have particularly been implicated in GB although the exact roles of these isoforms in different types of glioma cells remain unclear." (PMID 35052687, 2021). "In gliomas, the effect of ALDH1A1 predicting the clinical outcome was controversial." (PMID 26575197, 2015). "Recent research demonstrated that KIF4A knock-down can suppress the glioma stem cells marker expression including CD133, ALDH1A1, and ALDH1A3, meanwhile, KIF4A over-expression can promote the epithelial-to-mesenchymal transition (EMT) of glioma." (PMID 38937742, 2024). "We treated U87 cells, a glioma cell line, with sphere-forming media and observed that the expression of CSC marker proteins, including CD133, ALDH1A1, and ALDH1A3, was diminished in the group where KIF4A expression was knocked down." (PMID 38067227, 2023). "By whole-genome expression profiling data, we compared the mRNA expression level of ALDH1A3 and ALDH1A1 in low-grade gliomas (LGG, n = 122) and high-grade gliomas (HGG, n = 179)." (PMID 26575197, 2015). "Meanwhile, the mRNA expression level of ALDH1A1 and ALDH1A3 in high and low grade gliomas were compared by TCGA whole transcriptome sequencing data." (PMID 26575197, 2015). "Overexpression of ALDH1A1 has also been described in human high-grade gliomas but is not uniform inside GBM and is typical of cells located at the periphery of the tumors with a classical transcriptional subtype that have the worst prognosis." (PMID 39001459, 2024).
glioma (continued). "Analysis of the TCGA dataset showed that ALDH16A1, ALDH3B1, ALDH1A3, ALDH3A1, ALDH7A1 were significantly increased in IDH wildtype gliomas, while ALDH2, ALDH6A1, ALDH5A1, ALDH1A1, ALDH1L2, ALDH18A1, ALDH1B1 expression were higher in IDH mutant gliomas than IDH wildtype gliomas." (PMID 35116021, 2021). "We provide evidence that human GSCs express uniformly ALDH1A3 but not the ALDH1A1 isoform, whereas non-stem glioma cells express both isoforms at comparable levels." (PMID 35052687, 2021). "Notably, ALDH1A3, rather than ALDH1A1, is predominantly expressed in GSCs, whereas non-stem glioma cells comparably express both isoforms." (PMID 39519068, 2024). "Although the expression of ALDH1A3 is not restricted solely to GSCs, the composite ALDH1A3+/ALDH1A1-phenotype is a characteristic trait of GSCs whereas the concomitant expression of both ALDH1A3 and ALDH1A1 isoforms appears to be associated with glioma cells lacking stemness." (PMID 35052687, 2021). "However, we were not able to detect significant ALDH1A1 expression in either glioma cell line, even though earlier reports indicated that LN-18 had high ALDH1A1 protein levels." (PMID 28129349, 2017). "Thus, we think that ALDH1A1 may not be an ideal indicator in gliomas." (PMID 26575197, 2015).
non-small cell lung carcinoma (37 papers, 2008 to 2024). A group of at least three distinct histological types of lung cancer, including non-small cell squamous cell carcinoma, adenocarcinoma, and large cell carcinoma. "Increased ALDH1A1 expression was associated with poor survival in a cohort of non-small cell lung cancer (NSCLC) patients." (PMID 26783961, 2016). "However, in non-small cell lung carcinomas, loss of ALDH1A1 expression was suggested to promote carcinogenesis, particularly in smoking-related adenocarcinomas." (PMID 24485040, 2014). "ALDH1A1 was also shown to activate Akt signaling in non-small cell lung cancer and esophageal squamous cell carcinoma; however, the mechanism by which ALDH1A1 induces Akt phosphorylation is unknown." (PMID 38539211, 2024). "In this respect, Srinual and coworkers have established that vanillin suppresses cancer stemness phenotypes in the human non-small cell lung cancer NCI-H460 cell line through the downregulation of CD133 and ALDH1A1 and the associated transcription factors, Oct4 and Nanog." (PMID 32752227, 2020). "Targeting these highly expressed metabolic enzymes may be a suitable strategy to overcome cisplatin resistance, as has previously been demonstrated for Aldh1a1 in non-small-cell lung cancer (NSCLC)." (PMID 31189116, 2019). "Additionally, cisplatin exposure has been shown to select for resistant ALDH1A1-positive cells in non-small cell lung cancer." (PMID 30308036, 2018). "Notably, siRNA-mediated transient silencing of ALDH1A1 inhibited cell migration in human H2087 non-small cell lung cancer cells and invasion in A498 human renal carcinoma cells." (PMID 26242870, 2015). "There is gene amplification of ALDH1A1, ALDH1A3, or ALDH3A1 or upregulation of mRNA in 31% of non-small cell lung cancers." (PMID 36768694, 2023). "DIMATE, an irreversible inhibitor of ALDH1A1 and ALDH1A3, was cytotoxic for non-small cell lung cancer cell lines and effective against orthotopic xenografts and enhanced cisplatin chemotherapy." (PMID 36768694, 2023). "Aldehyde dehydrogenase1A1 (ALDH1A1) and CD133 are promising candidate of CSC markers in non-small cell lung cancer (NSCLC)." (PMID 35087112, 2022). "Aldehyde dehydrogenase isozymes ALDH1A1 and ALDH3A1 are highly expressed in non small cell lung cancer." (PMID 19025616, 2008). "Moreover, in A549GSC and H1650GSC cells, treatment with atRA was shown to dramatically lower the IC50 values for gefitinib, an ATP-competitive EGFR tyrosine kinase inhibitor used in non-small cells lung cancer (NSCLC) treatment, and the high expression of ALDH 1 family member A1 (ALDH1A1) and CD44." (PMID 36902427, 2023). "Furthermore, a decreased level of ALDH1A1 has been revealed in neoplastic cells of non-small-cell lung carcinoma compared to non-neoplastic epithelial cells by immunohistochemistry, with this decrease tended to be correlated with stronger proliferative activity." (PMID 32899940, 2020).
lymph node metastasis (32 papers, 2010 to 2026). "High expression of ALDH1A1 was found to be associated with higher likelihood of lymph node metastasis." (PMID 41228340, 2025). "A high frequency of ALDH1A1+ cells was found to be associated with lymph node metastasis (p = 0.035, Chi-Square test)." (PMID 41228340, 2025). "ALDH1A1 expression also positively correlated with the Union for International Cancer Control stages, invasion depth, and lymph node metastasis of esophageal squamous cell carcinomas and was associated with shorter survival of patients." (PMID 26783961, 2016). "Overexpression of ALDH1A1 (P < 0.001), larger tumor size (P < 0.001), prominent serosal invasion (P < 0.001) and lymph node metastasis (P < 0.001) were significantly associated with the poor OS rate of gastric cancer patients." (PMID 25253129, 2014). "ALDH1A1 protein expression was significantly associated with depth invasion, lymph node metastasis and stage of disease (all P < 0.05)." (PMID 25253129, 2014). "We found that ALDH1A1 was significantly associated with depth invasion, lymph node metastasis and stage of disease." (PMID 25253129, 2014). "Low ALDH1A1 expression was linked to regional lymph node metastasis (p = 0.01)." (PMID 41961804, 2026). "Higher frequency of ALDH1A1+ cells was found to be associated with lymph node metastasis." (PMID 41228340, 2025). "Furthermore, ALDH1A1 overexpression was associated with poor prognosis in patients subgroups stratified by tumor size, depth invasion and lymph node metastasis." (PMID 25253129, 2014). "The results showed that CDC45 and CDT1 were highly expressed in the lymph node metastasis group, while ALDH1A1 and ASAH1 were downregulated." (PMID 38589907, 2024). "We discovered elevated predominant cytoplasmic SOX9 expression in HGOC and found a strong correlation between cytoplasmic SOX9 and ALDH1A1 expression only in HGOC with lymph node metastasis." (PMID 35159173, 2022). "ALDH1A1 positive CSCs are found both in primary tumors originating from the oral cavity, oropharynx, hypopharynx and larynx and in lymph node metastases." (PMID 29112953, 2017). "As far as lymph node status was concerned, patients with lymph node metastasis tended to show elevated ALDH1A1 expression." (PMID 26783961, 2016). "As far as lymph node status was concerned, the patients with lymph node metastasis tend to show elevated ALDH1A1 expression." (PMID 25253129, 2014). "ALDH1A1 expression was highly correlated with factors that can lead to poor prognosis, such as extrathyroidal extension and lymph node metastasis." (PMID 24485040, 2014). "In addition, cases with ALDH1A1 expression are more likely to show development of lymph node metastasis, confirming that ALDH1A1 is a marker of poor tumor progression and prognosis." (PMID 34198652, 2021). "Notably, the correlation of ALDH1A1 with prominent serosal invasion and lymph node metastasis positivity suggested a potential role of ALDH1A1 in increased invasion and metastasis of gastric cancer." (PMID 25253129, 2014). "Together with the association of lymph node metastasis, and the similarity between the tumor center and lymph node metastasis, it is plausible that ALDH1A1-expressing cells might play a role in invasion as suggested before in inflammatory breast cancer or metastasis as suggested before in OSCC." (PMID 41228340, 2025). "The prognostic value of ALDH1A1 in different subgroups according to tumor size, depth of invasion and lymph node metastasis was also estimated, which appears that ALDH1A1 may serve as a powerful prognostic factor for patients with gastric cancer in different risk groups." (PMID 25253129, 2014). "Among upregulated oncogenic proteins in HGOC, we found that transcription factor SOX9 showed a strong correlation with stemness-regulating ALDH1A1 and was localized predominantly in the cytoplasm of HGOC with lymph node metastasis." (PMID 35159173, 2022).
lymph node metastasis (continued). "Furthermore, to evaluate the independent impact of ALDH1A1 overexpression on OS and RFS, a multivariate Cox regression model adjusted for tumor size, tumor site, depth of invasion, lymph node metastasis and ALDH1A1 expression was performed." (PMID 25253129, 2014). "Furthermore, PLK3 has significantly higher expression in bone metastases than in lymph node metastases, whereas low PLK3 expression upon ALDH1A1 gain is found mainly in lymph node metastases but not in bone marrow metastases." (PMID 38169509, 2024).
cervical carcinoma (30 papers, 2013 to 2024). A carcinoma arising from either the exocervical squamous epithelium or the endocervical glandular epithelium. "The expressions of P16INK4A, SOX2, and ALDH1A1 were performed by immunohistochemical staining of tumor samples from 139 cervical cancer patients with International Federation of Gynecology and Obstetrics stages Ib to IV." (PMID 30150594, 2018). "Since ALDH1A1 plays key role in maintaining the homeostasis of cervical cancer stem cell, we wanted to detect the sphere-forming ability of cells which were transfected with miR-23b." (PMID 28449663, 2017). "We found that miR-23b was under-expressed in cervical cancer stem cells to maintain high levels of ALDH1A1." (PMID 28449663, 2017). "As an intracellular enzyme that has a detoxifying role, ALDH1A1 has been identified as cancer stem cells marker for cervical cancer." (PMID 28449663, 2017). "They found that ALDH1A1 expression levels were also increased in the peripherical blood obtained from cervical cancer patients; thus, ALDH1A1 expression could be regarded as an indicator of cervical cancer." (PMID 35814382, 2022). "CD44 and ALDH1A1 are both considered to be typical CSC surface markers that can be used alone or in combination with other markers to isolate or enrich CSCs in a variety of tumor types including cervical cancer." (PMID 35860042, 2022). "We aimed to investigate the expression and clinical significance of cyclin-dependent kinase inhibitor 2A (P16INK4A), sex determining region Y-box 2 (SOX2), and Aldehyde dehydrogenase 1 family, member A1 (ALDH1A1) in cervical cancer treated with radiotherapy and cervical cell line models." (PMID 30150594, 2018). "Next, we further investigated whether the P16INK4A expression plus stem cell marker (SOX2 or ALDH1A1) was a good predictor of survival outcomes of cervical cancer patients treated with radiotherapy." (PMID 30150594, 2018). "We hypothesized that the higher levels of ALDH1A1 in cervical cancer stem cells are partially attributable to the deregulation of miRNAs." (PMID 28449663, 2017). "ALDH1A1 has been proved as one marker for cervical cancer stem cells." (PMID 28449663, 2017). "Results showed that miR-23b was consistently down-regulated in sphere-forming cells derived from four cervical cancer cells, suggesting that it may be good candidate for targeting ALDH1A1." (PMID 28449663, 2017). "Together, these data suggest that miR-23b could change the stemness of cervical cancer stem cells, probably via inhibiting the expression of ALDH1A1." (PMID 28449663, 2017). "Depletion of P16INK4A promoted chemoresistance and radioresistance of cervical cancer cells increased the expression of SOX2 and ALDH1A1 and exhibited higher self-renewal ability." (PMID 30150594, 2018). "ALDH1A1, an early stem cell differentiation marker and a cancer marker, was mainly expressed below the cut-off for cervical cancer in our study, indicating no cases of cervical carcinoma." (PMID 39508903, 2024). "It was found that the transcription and expression of the ALDH1A1 and OCT4 proteins were significantly higher in the cervix of patients with CIN II-CIN III and squamous cell carcinoma of the cervix compared with normal controls; these proteins can be biomarkers in cervical cancer." (PMID 34830452, 2021).
triple-negative breast carcinoma (30 papers, 2011 to 2025). An invasive breast carcinoma which is negative for expression of estrogen receptor (ER), progesterone receptor (PR), and human epidermal growth factor receptor 2 (HER2). "The presence of ALDH1A1 is associated with triple-negative breast cancer which is known to confer a poor prognosis, while patients receiving neoadjuvant cyclophosphamide had worse clinical outcomes if ALDH1A1 is expressed." (PMID 26203310, 2015). "The aim of this study was to investigate the role of ALDH1A1 in radiation resistance and redox stress in triple negative breast cancer (TNBC)." (PMID 40076923, 2025). "For instance, a prior report described that EB suppressed triple-negative breast cancer metastasis through reducing aldehyde dehydrogenases 1 family member A1 (ALDH1A1) expression both in vitro and in vivo." (PMID 39907426, 2025). "We observed an increase of Nanog only in MDA-MB-231 and SUM159PT triple-negative breast cancer cells and an increase of Notch1, Aldh1a1 and Aldh1a3 only in the SUM159PT cell line." (PMID 32610610, 2020). "One protein correlated with triple-negative breast cancer meriting a discussion is ALDH1A1, a detoxifying enzyme responsible for oxidizing intracellular aldehydes." (PMID 22110952, 2011). "To investigate the role of ALDH1A1 in radiation resistance, we used CRISPR/Cas9 to generate the genetic knockout (KO) of ALDH1A1 in the triple-negative breast cancer (TNBC) cell line SUM159." (PMID 40076923, 2025). "Pretreatment with a sulforaphane compound had in vivo tumor inhibitory effects, which were mediated through reduced Cripto and other stem cell markers, ALDH1A1, Nanog, and homologue CRIPTO-3 expression in triple negative breast cancer." (PMID 32517087, 2020). "Our data provide extensive evidence to demonstrate that KIF11 inhibitors showed pronounced antitumor activity, acting in key points of tumorigenesis and cancer progression in in vivo xenograft model of triple negative breast cancer, like down-regulation of KIF11 and ALDH1-A1." (PMID 34548908, 2021). "In addition, no studies have specifically evaluated the role of ALDH1A1 in predicting prognosis of triple-negative breast cancer (TNBC: estrogen receptor negative (ER-), progesterone receptor negative (PR-), human epidermal growth factor receptor 2 negative (HER2-))." (PMID 26462023, 2015).